ENSG00000238410
Synonyms: LOC124906189
Gene: Small nucleolar RNA gene on chromosome 2 (75,489,576 to 75,489,710, forward strand). Ensembl gene ENSG00000238410.
Gene Ontology:
Biological process: RNA processing
Cellular component: nucleolus
Homologues: Orthologues: rat LOC120094022 (73% identical). Paralogues in human: SCARNA18 (79% identical), SCARNA18B (79% identical).